ABCB1 (ATP binding cassette subfamily B member 1)
Diseases named in the same sentence as ABCB1 in open-access papers (continued):
Sharing a sentence is not in itself a finding about the gene and the disease.
cancer (continued). "Our results here revealed that multidrug-resistant cancer cells overexpressing ABCB1 or ABCG2 can be significantly resensitized by TMP195." (PMID 31905792, 2019). "Particularly, P-Gp (also known as ABC subfamily B1 or ABCB1) having a broad substrate specificity is a major player in therapy resistant cancers." (PMID 30818757, 2019). "At the cellular level, multidrug resistance (MDR) transporters such as P-glycoprotein (ABCB1) play an important role in cancer drug resistance by reducing the concentration of chemotherapeutics below a cell-killing threshold." (PMID 31053883, 2019). "Relapsed cancer cells, that have an aggressive phenotype, display an overexpression of the ATP-binding cassette transporter ABCB1 gene product and a high expression of the efflux pump P-glycoprotein (P-gp)." (PMID 30795552, 2019). "We mainly found that midostaurin, at non-toxic concentrations (200 and 500 nM), can significantly overcome ABCB1-mediated MDR in a series of cancer cell lines in a concentration-dependent manner." (PMID 31275850, 2019). "The main transporters expressed in cancer cells include P-glycoprotein (Pgp/ABCB1), multidrug resistance related proteins (MRPs/ABCCs), and breast cancer resistance proteins (BCRP/ABCG2)." (PMID 31117237, 2019). "The authors observed this regulatory axis miR-491-3p/Sp3/ABCB1 in cell lines and tissue from cancer patients." (PMID 35582590, 2019). "We discovered that TMP195 resensitizes ABCB1-overexpressing cancer cells to paclitaxel, colchicine, and vincristine, as well as resensitizes ABCG2-overexpressing cancer cells to mitoxantrone, SN-38, and topotecan in a concentration-dependent manner." (PMID 31905792, 2019). "Selected preparations were tested for anticancer efficacy in cancer cell lines, including cell lines that express ABCB1." (PMID 31728254, 2019). "In contrast, the effect of colchicine on ABCB1-overexpressing KB-V-1 cancer cells was significantly reduced (from approximately 8% basal level to 12% of early and late apoptosis), presumably due to ABCB1-mediated efflux of colchicine." (PMID 31905792, 2019). "Presumably, the treatment with VCR appears to enhance the recycling back to plasma membrane of ABCB1, after EVs were endocytosed by recipient cancer cells." (PMID 31830995, 2019). "Among many of the endosomal Rab proteins, Rab5 are widely known to regulate ABCB1 trafficking and recycling in cancer cells." (PMID 31830995, 2019). "To this end, we explored the potential mechanism and chemosensitizing effect of TMP195 in multidrug-resistant cancer cells overexpressing ABCB1, ABCC1 or ABCG2." (PMID 31905792, 2019). "Expressed in cancer cells, ABCB1, ABCG2 or ABCC1 mediate the efflux of chemotherapeutics, allowing the survival of multidrug-resistant clones despite toxic chemotherapy." (PMID 30863990, 2019). "The overexpression of P-gp/ABCB1 enables cancer cells to resist many currently available chemotherapeutics." (PMID 30841620, 2019). "Vincristine is also an ABCB1 substrate, and vincristine-adapted cancer cell lines often display enhanced ABCB1 levels." (PMID 31501742, 2019). "MTT assay in vitro and xenograftes in vivo were used to investigate reversal effect of FW-04-806 on MDR in ABCB1 or ABCG2 overexpressing cancer cells." (PMID 31472682, 2019). "Other phytochemicals such as curcumin and quercetin prevent ABCB1 function reversing MDR in human cancer cell lines." (PMID 31921125, 2019). "In the present study, we evidenced the existence of intercellular ABCB1 transfer from drug-resistant cancer cells to sensitive cancer cells." (PMID 31830995, 2019). "ABCB1 is a transporter firstly identified, and has the greatest influence in mediating efflux of various kind of drugs including anti-cancer agents." (PMID 29765522, 2018).
cancer (continued). "Of these, ABCB1/P-gp, ABCC1/MRP1, and ABCG2/breast cancer resistance protein are primarily associated with MDR." (PMID 29670920, 2018). "Wnt β-catenin signaling plays an important role in the maintenance of chemoresistance in cancer cells by modulating the transcription of multidrug resistance genes ABCB1/MDR-1, which are also expressed in normal somatic stem cells." (PMID 30591679, 2018). "Over expression of a range ofATP-dependent efflux pumps, particularly ABCB1 is a widely reported mechanism of cancer cell MDR." (PMID 31223218, 2018). "In primary cancer tissues ABCB1 and ABCG2 expression levels were different in the two NSCLC subtypes." (PMID 28340578, 2017). "Whereas ABCB1 has long dominated the “stage” of transporter-related drug resistance in cancer, other ABC transporters became clinically relevant in the 1990s." (PMID 29317984, 2017). "Switching on and off of an array of genes such as BRCA1, BRCA2, Akt1, ERCC1 and ABCB1 were identified to modulate sensitivity toward chemotherapy in cancer patients." (PMID 27980217, 2017). "Since pretazettine affects the p-glycoprotein ABCB1, it can be developed as a supportive agent to other cancer drugs, allowing them to overcome drug resistance." (PMID 28208712, 2017). "In resistant CEM/ADR cells, sesquiterpenes did not increase DOX efficacy, although they significantly increased accumulation of DOX (up to 10-times) and rhodamine-123 (substrate of efflux transporter ABCB1) within cancer cells." (PMID 28632185, 2017). "P-glycoprotein (P-gp, ABCB1) over-expression, causing a multi-drug resistant (MDR) phenotype, is a major problem in cancer chemotherapy that urgently requires novel approaches." (PMID 28125071, 2017). "In several cancer entities, aberrant ABCB1 or ABCG2 methylation was shown, i.e. in leukemia or solid tumors and was also observed in drug-resistance." (PMID 29190894, 2017). "Firstly, while resistant cells express increased levels of ABCB1 and Pgp, they are almost undetectable in the parental cancer cells and in the co-treated cells." (PMID 29137448, 2017). "Some RTK inhibitors have been shown to inhibit the drug efflux function of ABCB1, thus overcoming the resistance of cancer cells to traditional chemotherapeutic drugs." (PMID 28455956, 2017). "ABCG2, together with ABCB1, is one of the major efflux transporters of TKIs and is strongly expressed in drug-resistant cancer cells." (PMID 29190894, 2017). "The major ABC superfamily transporters associated with multidrug resistance development were ABCB1, MRP2/ABCC2, and BCRP/ABCG2, which were often enriched with cells cancer stem cell-like phenotypes." (PMID 28903328, 2017). "The results not only uncover a novel mechanism of MUC1-induced chemoresistance but also implicate ABCB1 as a potential therapeutic target in cancer cells." (PMID 28796259, 2017). "ABCB1 is a gene which is highly expressed in CSCs that encodes for the P-glycoprotein (P-pg)/ multidrug resistance protein (MDR), protecting the cancer cell from anticancer drugs." (PMID 27454254, 2016). "One of the reasons for these failures is that ABCB1 inhibitors did not only interfere with the ABCB1 present on cancer cells but also with ABCB1 at physiological cellular and tissue barriers." (PMID 26887049, 2016). "In conclusion, our results show that PPD12 antagonizes ABCB1-mediated cancer cell MDR in vitro and in vivo by directly blocking the drug-efflux functions of ABCB1." (PMID 26824187, 2016). "Over expression of ABCB1 in cancer cells results in resistance to drugs from different classes such as vinca alkaloids, taxanes, anthracyclines, epipodophyllotoxines." (PMID 28119610, 2016). "Non‐toxic concentrations Saq‐nitric oxide caused sensitization of ABCB1‐, ABCC1‐ or ABCG2‐overexpressing cancer cells to chemotherapy." (PMID 26864945, 2016).
cancer (continued). "Our findings also indicate the contribution of secreted signals of PTX-resistant cancer cells with 5-FU cross-resistance to the outgrowth and regulation of FOXO3a-mediated ABCB1 transcription, leading to a drug transporter efflux increase." (PMID 27284014, 2016). "In this regard, antiretrovirals, cardiovascular drugs, anti‐cancer agents, antibiotics, and a plethora of other APIs are substrates of efflux transporters such as ABCB1 and ABCCs." (PMID 27774308, 2016). "On the other hand, cancer drug resistance limits its use, and ABCB1(MDR1, P-gp), ABCC1 (MRP1) as well as other transporters have been characterized in previous studies for their roles in drug resistance." (PMID 26824188, 2016). "In the case of afatinib and PHA-665752 resistance, upregulation of ABCB1 expression was connected with selection for a cancer stem cell phenotype and an epithelial-to-mesenchymal transition (EMT) switch." (PMID 27367030, 2016). "Promoter methylation was found to be an important mechanism in gene regulation of ABCB1 in parental cancer cell lines and their drug-resistant sublines." (PMID 27689338, 2016). "Cancer cells overexpressing ABCB1 and/or ABCC1 are also resistant to Vinca alkaloids (e.g. vincristine) and colchicine." (PMID 27689338, 2016). "Our study identifies that the response of TUBB3 from FOXO3a-regulated ABCB1 is a critical feedback mechanism to genetically identify cross-resistance in PTX-resistant cancers and its tumor progression." (PMID 27284014, 2016). "To confirm the ability of PPD12 to antagonize ABCB1-mediated cancer MDR in vivo, we generated KB/VCR xenograft models in nude mice." (PMID 26824187, 2016). "In contrast, in some cancer cell lines, promoter methylation of ABCB1 was found to be inversely correlated with gene expression at the mRNA and/or protein level." (PMID 27689338, 2016). "Ginsenoside Rg3 is metabolized to 20(S)-protopanoxadiol (PPD) by intestinal bacteria, and this metabolite also has been reported to have anti-cancer activity and via inhibition of ABCB1." (PMID 26824187, 2016). "Extrusion of chemotherapeutics by ATP-binding cassette (ABC) transporters like ABCB1 (P-glycoprotein) represents a crucial mechanism of multidrug resistance in cancer therapy." (PMID 26319048, 2016). "The 19 human cancer cell lines investigated in the present study were found to differ in the methylation status of the ABCB1 and ABCG2 promoter." (PMID 27689338, 2016). "ABCB1, ABCC1 and ABCG2 are the ABC transporters most frequently been associated with MDR in cancers." (PMID 27689338, 2016). "In the light of our here presented data, this implies that cancer cells can utilize physiological signal circuits, as in this case ABCB1 activation by ET-1/ETAR signaling in endothelial cells, to survive systemic treatment options." (PMID 27367030, 2016). "These proteins have been suggested to induce cancer cell chemoresistance by reducing cell sensitivity to apoptosis and upregulating the expression of the multidrug resistance protein ABCB1." (PMID 27769054, 2016). "In several cancer cell lines, e.g. ZR-75-1, A549 and A2780, the promoter region of ABCB1 was methylated rather heterogeneously." (PMID 27689338, 2016). "Although the drug transporters ABCG2, ABCB1 and ABCC1 have been majorly implicated in cancer drug resistance, recent studies have associated ABCC3 with multi drug resistance and poor clinical response." (PMID 27171227, 2016). "Non-toxic concentrations of the PPD derivative PPD12 sensitized ABCB1-overexpressing cells to their anti-cancer substrates better than either the parental PPD or inactive PPD11." (PMID 26824187, 2016). "H460 cells expressed higher levels of ABCB1 (250.43 fold) and several other cancer drug resistance genes than A549 cells, but in general most of the human cancer drug resistance genes included were expressed more highly in A549 cells than H460 cells." (PMID 27765909, 2016).
cancer (continued). "In this study, we demonstrate that PPD12, compared to its parental compound PPD and inactive compound PPD11, sensitizes ABCB1-medidated MDR cancer cells to chemotherapeutic agents in vitro and in vivo." (PMID 26824187, 2016). "Together, our results demonstrated that trametinib significantly enhanced the sensitivity of ABCB1-substrate chemotherapeutic agents in the ABCB1-overexpressing cells, suggesting trametinib is able to antagonize ABCB1-mediated cancer MDR in vitro." (PMID 25915534, 2015). "Side population (SP) isolation from a number of cancer cell lines has shown that the expression of ABCB1 is upregulated in the SP compared to the normal population." (PMID 26649310, 2015). "Elevated expression of membrane drug efflux pumps such as P-glycoprotein (P-gp, ABCB1), multidrug resistance protein 1 (MRP-1, ABCC1) and ABCG2 is a frequent cause of MDR in human cancers." (PMID 25635866, 2015). "Overexpression of ABCB1 on the surface of cancer cells is considered as the most common explanation of MDR." (PMID 26506420, 2015). "Recently, we have shown that the ATP-binding cassette (ABC) transporter ABCB1 interferes with the anti-cancer activity of the pan-aurora kinase inhibitor tozasertib (VX680, MK-0457) but not of the aurora kinase A and B inhibitor alisertib (MLN8237)." (PMID 26415506, 2015). "Taken together, these results indicated that combination of nobiletin with PTX elicited significantly higher cytotoxic response in ABCB1 overexpression MDR cancer cells." (PMID 26689156, 2015). "P-glycoprotein (P-gp; multidrug resistance pump 1, MDR1; ABCB1) is a plasma membrane efflux pump that when activated in cancer cells exports chemotherapeutic agents." (PMID 25866761, 2015). "Among them, ABCB1 is the most well-studied target to regulate cancer drug resistance and develop chemosensitizing agents." (PMID 26431273, 2015). "In this study, we performed a series of experiments to investigate the reversal effect of nobiletin on ABCB1 overexpressing cancer cell lines to chemotherapeutic agents including paclitaxel (PTX), doxorubicin (DOX), docetaxel and dounorubicin." (PMID 26689156, 2015). "The RNA levels of two ATP-binding cassette transmembrane proteins (ABC), ABCG2 (known as breast cancer resistance protein) and ABCB1, were dramatically up-regulated in the irinotecan-resistant cells." (PMID 25973791, 2015). "Here, we found that ceritinib remarkably enhanced the efficacy of chemotherapeutic drugs in ABCB1 or ABCG2 over-expressing cancer cells in vitro and in vivo." (PMID 26556876, 2015). "Our findings advocate further clinical investigation of combination chemotherapy of cetuximab and conventional chemotherapeutic drugs in ABCB1 overexpressing cancer patients." (PMID 26506420, 2015). "Our previous studies showed that several sipholane triterpenes, sipholenol A, sipholenone E, sipholenol L and siphonellinol D, have potent reversal effect for multidrug resistance (MDR) in cancer cells that overexpressed P-glycoprotein (P-gp/ABCB1)." (PMID 25874923, 2015). "Enzastaurin has been reported to display enhanced activity in combination with various anti-cancer drugs [see e.g. 11, 13, 17, 19, 41; 58–60] including ABCB1, ABCG2, and/or ABCC1 substrates such as paclitaxel, docetaxel, erlotinib, and doxorubicin." (PMID 25749379, 2015). "To investigate the effects of trametinib on ABCB1-mediated MDR in cancer cells, we firstly examined the cytotoxicity of trametinib in two ABCB1-overexpressing cells KBV200 and MCF-7/ADR and their parental cells KB and MCF-7 by MTT assay." (PMID 25915534, 2015). "ABCB1, the first ABC transporter to be identified, is reportedly associated with the failure of chemotherapy treatment of various cancers, including breast, colon and lung cancers." (PMID 25860815, 2015). "Side population isolation from cancer cell lines has demonstrated that the expression of ABCB1 is upregulated in the SP when compared to the normal population." (PMID 26649310, 2015).
cancer (continued). "In this study, we demonstrate that trametinib significantly sensitizes ABCB1-medidated MDR cancer cells to chemotherapeutic agents in vitro and in vivo by directly antagonizing the drug-efflux activity of ABCB1." (PMID 25915534, 2015). "The three major ABC-transporters associated with DR in human oncology are ABCB1 or P-gp, ABCC1 or MRP1, and ABCG2 or BCRP, and have been demonstrated in canine cell lines, healthy dogs and dogs with cancer." (PMID 29061939, 2015). "The possibility of specifically targeting cancer stem cells expressing multi-drug pumps (e.g. ABCB1) was described by Beth Coyle." (PMID 26517919, 2015). "To investigate the mechanism of the powerful reversing effect of nobiletin to PTX in ABCB1 overexpression cancer cells, we examined the effects of nobiletin on the drug transport activity of ABCB1 and the expression of P-gp protein." (PMID 26689156, 2015). "Potent inhibitors against ABCB1 have been developed to overcome cancer multidrug resistance (MDR), but the therapeutic applications were unsuccessful in major clinical trials." (PMID 25699998, 2015). "Drug transporters such as P-glycoprotein (ABCB1) have been associated with chemotherapy resistance and are considered unfavorable prognostic factors for survival of cancer patients." (PMID 25275603, 2014). "The overexpression of ABCB1 confers significant resistance to a wide variety of compounds that are used in the chemotherapy of cancer." (PMID 25191874, 2014). "Since there are only limited number of ABCB1 inhibitors currently available, continued searches for activated molecular targets in chemoresistant cancer are crucial for the development of novel strategies for treating chemoresistant patients." (PMID 25401518, 2014). "Gain and amplification of 7q22.11q31.1 are associated with an increased expression of several genes postulated to be implicated in cancer, including RUNDC3B, PPP1R9A and ABCB1, a known multidrug resistance gene." (PMID 25057852, 2014). "Overexpression of ABCB1 in tumor tissues of cancer patients following chemotherapy is well established." (PMID 25401518, 2014). "Apparently morphologically normal tissue from cancer cases had significantly but only slightly lowered ABCB1 mRNA levels." (PMID 23977225, 2013). "The expression of MCSF in U87MG cells leading to cancer stem cell population further aggravated the resistive phenotype through an elevated increase in the expression of ABCB1 and mdm2 as compared to the treated U87MG cells." (PMID 24391839, 2013). "Recent findings have found that berberine and coptisine, which are the major active constituents of Coptis, were found to reverse ABCB1-mediated MDR in human MDR cancer cells." (PMID 23533531, 2013). "The potential candidates for ABCB1 inhibition can also be determined based on their ability to interfere with the drug resistance of ABCB1-expressing cancer cell lines or compete for direct binding to the transporters." (PMID 23593196, 2013). "On the other hand, ABCB1 also transports a wide range of antineoplastic drugs such as doxorubicin, vincristine, paclitaxel, and epipodophyllotoxins out of the cancer cells." (PMID 23349819, 2013). "Using this approach we successfully identify genes involved in paclitaxel resistance in a variety of cancer cell lines, including the multidrug transporter ABCB1, a previously identified major paclitaxel resistance gene." (PMID 23442791, 2013). "MDR is often mediated by drug efflux transporters such as P-glycoprotein (P-gp, encoded by ABCB1), which are often overexpressed in cancer cells." (PMID 23527297, 2013). "ABCB1 is largely recognized for its role in enabling cancer cells to evade response to treatment via the efflux of chemotherapeutic agents." (PMID 23593196, 2013). "Identification of ABCB1 modulators is of great clinical interest, as these compounds are capable of reversing drug resistance and improving cancer chemotherapy." (PMID 24376706, 2013).